BID (BH3 interacting domain death agonist)
Diseases named in the same sentence as BID in open-access papers (continued):
Sharing a sentence is not in itself a finding about the gene and the disease.
autoimmune thyroiditis (1 paper, 2014). "However, mice with thyroid-specific BID overexpression are at high risk of development of autoimmune thyroiditis induced by known pathogenic factors such as iodine." (PMID 24957380, 2014). "Our data demonstrate that increased thyroid expression of BID facilitates the development of autoimmune thyroiditis induced by iodine uptake." (PMID 24957380, 2014). "To test this hypothesis we first established a transgenic mouse line that expresses human BID specifically in the thyroid, and then tested whether the overexpression of BID alone is sufficient for the development of autoimmune thyroiditis." (PMID 24957380, 2014). "Thus, apoptosis of thyrocytes in EAT or autoimmune thyroiditis is dependent on both cell death receptors and mitochondrial elements, in which BID plays a critical role." (PMID 24957380, 2014). "To test whether the genetic changes in BID play a role in the development of autoimmune thyroiditis, we successfully developed a transgenic mouse line in which BID is specifically over-expressed in the thyroid." (PMID 24957380, 2014). "Our study has demonstrated that the increasing BID expression specifically in thyroid does not cause autoimmune thyroiditis." (PMID 24957380, 2014). "We therefore hypothesized that the overexpression of BID plays a positive role in the development of autoimmune thyroiditis." (PMID 24957380, 2014). "In this study, we employed CBA/J (H-2 k) mice to examine whether the overexpression of BID can overcome this resistance, and sensitize these mice to iodine-induced autoimmune thyroiditis." (PMID 24957380, 2014). "However, upon ingestion of iodine in the drinking water, autoimmune thyroiditis does develop in Tg-BID transgenic mice, as shown by a significant increase in anti-Tg antibody and mononuclear cell infiltration in the thyroid glands in 30% of mice tested." (PMID 24957380, 2014).
chronic myelomonocytic leukemia (1 paper, 2016). A myelodysplastic/myeloproliferative neoplasm which is characterized by persistent monocytosis, absence of a Philadelphia chromosome and BCR/ABL fusion gene, fewer than 20 percent blasts in the bone marrow and blood, myelodysplasia, and absence of PDGFRA or PDGFRB rearrangement. "Young mice deficient in BID have no major hematological defects, whereas aged mice develop neutrophilia and many succumb to a hematopoietic malignancy resembling human chronic myelomonocytic leukemia (CMML)." (PMID 28066751, 2016).
coronary atherosclerosis (1 paper, 2018). Atherosclerosis of the coronary vasculature. "Decreased BID expression in heart tissue significantly associated with myocardial infarction (p=7.55×10−3) as well as coronary atherosclerosis (p=8.26×10−3), and ischemic heart disease (p=9.7×10−4)." (PMID 30281024, 2018).
depression (1 paper, 2013). "Increases in apoptotic activity via BID may underlie the increased depression-like behaviors observed in some human adolescents treated with PRX, especially considering the recent demonstration of antidepressant effects of the BID inhibitor, BI-11A7." (PMID 23847536, 2013).
dermatitis (1 paper, 2014). An inflammatory process affecting the skin. "TNFR1-induced apoptosis can proceed through caspase-8 and BID, but reduction in or loss of these players generally did not suppress inflammation, although Casp8 heterozygosity significantly delayed dermatitis." (PMID 25443632, 2014). "Given the prominent role that caspase-8 plays in the dermatitis, it would be expected that if the intrinsic apoptosis pathway is engaged it should be downstream of caspase-8 and require cleavage of the BH3 protein, BID." (PMID 25443632, 2014).
EBV infection (1 paper, 2021). "One was the Epstein-Barr virus infection pathway (q-value=0.025), represented by four upregulated genes (CDKN1A, NFKB2, RELB, and PDIA3) and two downregulated genes (BID and HLA-A)." (PMID 33785040, 2021). "BID and CDKN1A are both involved in the pathway of EBV infection that has been previously discussed." (PMID 33785040, 2021).
esophageal cancer (1 paper, 2021). A primary or metastatic malignant neoplasm involving the esophagus. "In our studies with the esophageal cancer cell system, we found a decrease in BID in the three cell systems." (PMID 34830970, 2021).
gastric adenocarcinoma (1 paper, 2016). "Two proteins were down-regulated in AFP producing gastric adenocarcinoma, including ASC-R and BID." (PMID 27057629, 2016). "However, to our knowledge, dysregulation of cyclin D1, RANKL, LSD1, Autotaxin, Calpain2, XIAP, IGF-Irβ, ASC-R and BID in AFP producing gastric adenocarcinoma has not been reported before." (PMID 27057629, 2016).
Graves disease (1 paper, 2018). Graves' disease is an autoimmune disorder that leads to overactivity of the thyroid gland (hyperthyroidism).It is caused by an abnormal immune system response that causes the thyroid gland to produce too much thyroid hormones. "Therefore, the greater BID (apoptotic) expression in the thyrocytes and lower expression of MCL-1 (antiapoptotic) in lymphocytes may lead to the routine use of these drugs in therapy for Graves' disease, changing its indication." (PMID 30018638, 2018).
hemorrhage (1 paper, 2025). Loss of blood from the vascular compartment to the exterior or into nonvascular body space as a result of rupture or severance of the blood vessels. "BID plays a critical role in the regulation of apoptosis following intracerebral hemorrhage and serves as a key biomarker in the apoptotic process after hemorrhage." (PMID 40093739, 2025).
Hepatic steatosis (1 paper, 2017). Steatosis is a term used to denote lipid accumulation within hepatocytes. "BID-deficient mice were protected from Fas-induced mitochondrial dysfunction and hepatic steatosis." (PMID 28883393, 2017). "Mice with genetic or pharmacological inhibition of BID are protected from Fas-mediated impairment of mitochondrial oxidation and hepatic steatosis." (PMID 28883393, 2017).
Hypoglycemia (1 paper, 2021). A decreased concentration of glucose in the blood. "BID inhibition also prevented nuclear translocation of the pro-apoptotic factor AIF in models of hypoxia–hypoglycemia-induced neuronal cell death, although the role of caspase 8 in AIF release from mitochondria was not elucidated in this study, and a role for PARP activation was proposed." (PMID 34708044, 2021).
hypothyroidism (1 paper, 2025). Abnormally low levels of thyroid hormone. "We further observed significantly elevated levels of both sphingosine and BID in the umbilical cord blood of the hypothyroidism group compared to the controls." (PMID 41573549, 2025). "Quantitative analysis of protein differences revealed that the level of BH3 interacting BID was significantly higher in the hypothyroidism group than in the control group." (PMID 41573549, 2025). "We propose that the role played by the upregulation of Sph and BID in hypothyroidism during the first half of pregnancy may be as follows: the propensity for maternal oxidative stress increases during pregnancy inducing the production of reactive oxygen species (ROS)." (PMID 41573549, 2025). "The findings indicate that the upregulation of sphingomyelin may influence BID through the SSP to promote BID-mediated apoptosis, which is involved in the onset and development of hypothyroidism during pregnancy." (PMID 41573549, 2025).
inflammatory bowel disease (1 paper, 2011). A spectrum of small and large bowel inflammatory diseases of unknown etiology. "Targeting BID by small molecules has been proposed as a way to treat immune-mediated inflammatory disease including inflammatory bowel disease." (PMID 21827714, 2011).
intracerebral hemorrhage (1 paper, 2025). A cerebrovascular disorder characterized by bleeding into one or both cerebral hemispheres including the basal ganglia and the cerebral cortex. "First, although we validated the expression of BID and its relationship with apoptosis in a rat intracerebral hemorrhage model, we did not delve into its underlying mechanisms." (PMID 40093739, 2025).
ischemic stroke (1 paper, 2024). A stroke disorder caused by obstruction of blood flow to the brain, due to thrombotic (local blood clot formation) or embolic (due to a blood clot or other material traveling from another site) event. "In ischemic stroke, elevated chondriosomal Ca2+ levels result in the cleavage of BH3 interacting-domain death agonist (BID) into truncated BID (tBID), which interacts with B-cell lymphoma 2 (BCL2) antagonist/killer 1 (BAK), an apoptotic protein, at the mitochondrial membrane." (PMID 39133904, 2024).
liver cancer (1 paper, 2025). An epithelial or non-epithelial malignant neoplasm that arises from the liver. "From this study we concluded that sea cucumber Ps extract can inhibit proliferation of HepG-2 cells through downregulation of VEGF and induction of apoptosis in liver cancer cells via downregulation of survivin and Bcl2 expression and upregulation of BAX, BAK and BID expression." (PMID 40550816, 2025).
liver disease (1 paper, 2021). "Therefore, the downregulation of BID and HLA-A genes could improve liver disease and immune response." (PMID 33785040, 2021).
lung squamous cell carcinomas (1 paper, 2023). "Finally, in The Cancer Genome Atlas (TCGA), co-amplification of BCL2L13, BID, CRKL and MAPK1 was present in 0.5% of reported samples, being > 2% among sarcomas or lung squamous cell carcinomas." (PMID 37443114, 2023).
lupus (1 paper, 2024). "After treating cell cultures with the plasma of different mouse groups, the t-BID/BID ratio was significantly higher with lupus mouse plasma, and this effect was dampened with the plasma of the CLC group." (PMID 39061948, 2024). "In our study, the t-BID/BID ratio was increased in vitro after exposure of hippocampal cell cultures to lupus mouse plasma, whereas the CLC group plasma induced a significantly lower increase in the t-BID/BID ratio." (PMID 39061948, 2024).
mastitis (1 paper, 2014). Inflammation of breast tissue during lactation or postpartum due to an obstructed duct or infection. "Two of them were related to mastitis in a disease-induced mouse-model study: BID (BH3 interacting domain death agonist), which is a pro-apoptotic induced gene, and MAFF (v-maf avian musculoaponeurotic fibrosarcoma oncogene homolog F), which is related to cell proliferation." (PMID 24788864, 2014).
metabolic syndrome (1 paper, 2022). A cluster of metabolic risk factors for CARDIOVASCULAR DISEASES and TYPE 2 DIABETES MELLITUS. "The present study also suggests that targeting BID can be a potential therapeutic approach for metabolic syndrome." (PMID 36382356, 2022). "BID can mediate apoptosis in adipocytes or pancreatic β cells, whose demise may affect metabolic syndrome in some ways." (PMID 36382356, 2022).
metastatic melanoma (1 paper, 2014). A melanoma that has spread from its primary site to another anatomic site. "We evaluated pretreatment mRNA expression of BCL-2 family members, BCL-2, MCL-1, BCL-XL, BCL-W, BIM, and BID in tumors of patients with metastatic melanoma." (PMID 24983357, 2014).
metastatic tumors (1 paper, 2024). "High levels of BID occur in the thyroid tumors of TCGA in a Braf-like subtype, in metastatic tumors, and in the presence of nodal metastases." (PMID 38540271, 2024).
myeloid leukemia (1 paper, 2016). A clonal proliferation of myeloid cells and their precursors in the bone marrow, peripheral blood, and spleen. "Interestingly, phenotypical differences between the two different BID-KO mice strains have previously been described: The mice utilized in the two previous studies have been observed to develop spontaneous myeloid leukemia as they age." (PMID 26869884, 2016).
myeloid neoplasm (1 paper, 2016). Proliferation of myeloid cells originating from a primitive stem cell. "Pro-apoptotic BID is essential for normal hematopoiesis, and BID-deficient mice spontaneously develop fatal myeloid neoplasms indicating that BID is necessary to suppress leukemogenesis." (PMID 27613060, 2016).
myocardial infarction (1 paper, 2018). Gross necrosis of the myocardium, as a result of interruption of the blood supply to the area, as in coronary thrombosis. "A gene-based approach applied to a biobank, validated in two independent GWAS studies, reveals that decreased genetically determined BID expression associates with myocardial infarction (MI) susceptibility." (PMID 30281024, 2018). "BID coding SNPs associate with myocardial Infarction (MI) in humans and reveal helix-6 SNP M148T is critical for Bid’s regulation of mitochondrial function." (PMID 30281024, 2018).
myocardial ischemia (1 paper, 2024). A disorder of cardiac function caused by insufficient blood flow to the muscle tissue of the heart. "Furthermore, we evaluated whether PDCD4 and BID involving mitochondrial fission engage in the regulation of apoptosis in cardiomyocytes post MI to learn more about the pathophysiological significance of PDCD4 in myocardial ischemia injury." (PMID 38503934, 2024).
preeclampsia (1 paper, 2018). Preeclampsia is a hypertensive disorder of pregnancy that is characterized by new-onset hypertension with proteinuria presenting after 20 weeks of gestation, and depending on mild or severe forms may initially present with severe headache, visual disturbances, and hyperreflexia. "We found no preeclampsia-related changes in BAP31, CASP8 or BID, which can signal apoptosis through the extrinsic pathway and via the ER." (PMID 30455461, 2018).
thyroid tumor (1 paper, 2024). A benign or malignant neoplasm affecting the thyroid gland. "Interestingly, there was significant overexpression of BID in Braf-like thyroid tumors (n = 270) compared to normal (n = 58) and Ras-like (n = 118) thyroid tissues." (PMID 38540271, 2024). "In addition, the highest expression of BID was observed in metastatic thyroid tumors (n = 8) based on comparison to 502 thyroid tumor tissues and 58 normal thyroid tissues (p = 1.11 × 10−26)." (PMID 38540271, 2024).
viral hepatitis (1 paper, 2013). An acute or chronic inflammation of the liver parenchyma caused by viruses. "Furthermore, a recent report indicated that BID (a pro-apoptotic member) is down-regulated in a subset of HCCs in the context of viral hepatitis." (PMID 24376606, 2013).
ZIKV infection (1 paper, 2019). "Several genes involved in cell death (CASP1, TNFSF10, RIPK2, and BID) were also activated upon ZIKV infection." (PMID 30781519, 2019).
cancer (85 papers, 2001 to 2025). A tumor composed of atypical neoplastic, often pleomorphic cells that invade other tissues. "Consistently, some mutations in BID that reduce its killing potency have been noted in cancer, identifying a potential drug resistance mechanism." (PMID 39475598, 2024). "Our analysis above also predicts potential mechanisms of drug resistance, already found in cancer patients, i.e., selecting for mutations in alpha 6 of BID." (PMID 34931711, 2022). "Cytokine rhTRAIL induces apoptosis by selectively binding to DR4 and DR5 on cancer cells and initiates the caspase-activation cascade, leading to the truncation of BID." (PMID 40787732, 2025). "Other studies have highlighted the role of hyperthermia in enhancing rhTRAIL-induced apoptosis in cancer cells through caspase activation and the BID-Bax-mitochondrial-dependent apoptotic pathway." (PMID 40787732, 2025). "Enrichment analysis indicated that BID was significantly enriched in immune-related responses and cancer-related pathways." (PMID 38767695, 2024). "During our study, we had found BID upregulation in several cancer cell lines, accompanied by Chr22q11 amplification exclusively in one case." (PMID 37443114, 2023). "Our study confirms this process by showing the upregulation of caspase 3 and BID after treatment with the anti-cancer drugs PTX and Fis, which induce apoptosis in OvCa cells." (PMID 37990267, 2023). "We found that the human P14ARF gene and the activated, truncated segment of BID (tBID), when concomitantly expressed, synergistically induced intrinsic and extrinsic apoptosis in many different types of cancer cells." (PMID 36830797, 2023). "In this regard, our results open new avenues for the use of BID activation as a strategy to kill cancer cells that have become insensitive to BAX and BAK." (PMID 34931711, 2022). "Cathepsin B and Cathepsin D release into the cytosol promoted the cleavage and activation of BID, and Dcf1 also decreased the expression of Bcl‐2 to induce the release of proapoptotic factors and enhance the levels of cancer suppressors." (PMID 34799992, 2022). "The low cellular level of the BH3-interacting domain death agonist (BID) protein is a vital factor for the viability of various cancer cells." (PMID 34575464, 2021). "The expression of the BID gene in cancer cells of the WM793 line, treated with a fatty acid mixture extracted from CLA-enriched chicken egg yolks, increased 3-fold." (PMID 34371857, 2021). "As the caspase cascade plays a regulatory role in the apoptosis of various cancer cell lines, we examined the effect of CP-Mh on the expression of key molecules of the apoptotic signaling cascade, including Bax/Bcl-2 ratio, BID, Casp-9 and Casp-3." (PMID 33158052, 2020). "BID silencing partially protected cancer cells from BSB-induced mitochondrial depolarization, as evidenced by the decreased percentage of green-emitting JC-1 monomers compared to control." (PMID 31767857, 2019). "By using HeLa and Jurkat cells as in vitro cancer models, here we demonstrate that BID is rapidly mobilized upon BSB treatment and its presence is required for full cytotoxicity to occur." (PMID 31767857, 2019). "For example, overexpression of anti-apoptotic BCL-2 proteins confers a favorable prognosis in certain cancer types whereas genetic deletion of the pro-apoptotic BH3-only proteins BID and PUMA inhibits tumorigenesis in some settings." (PMID 25702873, 2015). "Previously, we showed that recombinant BID fused with TAT cell penetrating peptide (TAT-BID) allowed for controlled delivery of BID to different cancer cell lines and moderately sensitized some of them to TRAIL or slightly to camptothecin." (PMID 25760094, 2015). "Overexpression of the BH3-interacting domain death agonist (BID) protein sensitizes certain cancer cell lines to apoptosis induced by anticancer agents, particularly by those acting through death receptors (e.g. TRAIL)." (PMID 25760094, 2015).